FBXO7 (F-box protein 7)
Diseases named in the same sentence as FBXO7 in open-access papers (continued):
Sharing a sentence is not in itself a finding about the gene and the disease.
lung carcinoma (4 papers, 2015 to 2025). "It has been reported that FBXO7 is highly expressed in human lung cancer and colon cancer, suggesting a tumor-promoting role of FBXO7." (PMID 38839752, 2024). "Recent studies have demonstrated that FBXO7 is deregulated in several cancers, such as lung cancer, colon cancer and endometrial cancer." (PMID 38839752, 2024).
endometrial carcinoma (3 papers, 2023 to 2026). A malignant tumor arising from the epithelium that lines the cavity of the uterine body. "Consistent with our findings, previous studies have shown that FBXO7 functions as a tumor suppressor in various tumors, including HCC and endometrial carcinoma." (PMID 41507145, 2026).
hepatocellular carcinoma (2 papers, 2014 to 2024). A malignant tumor that arises from hepatocytes. "Here the authors identify FBXO7, an E3 ubiquitin ligase, inhibits serine synthesis in hepatocellular carcinoma by promoting ubiquitination and degradation of PRMT1 methyltransferase." (PMID 38839752, 2024). "FBXO7 can interact with three proteins including hepatoma upregulated protein, cIAP1, and the proteasome inhibitor protein PI31." (PMID 25029497, 2014).
lung squamous cell carcinoma (2 papers, 2013 to 2015). "In addition, Fbxo7 over-expression was observed in human tumour biopsies from lung squamous cell carcinoma and colon adenocarcinoma but was virtually absent from corresponding normal tissue, suggesting that Fbxo7 may be oncogenic in these tissue types." (PMID 24107298, 2013).
coronary artery disease (1 paper, 2022). "We entered FBXO7, RAD23A, and MKRN1 into the camp database and eventually identified 11 drugs that could be used to treat coronary artery disease, including doxorubicin, gabapentin, suxibuzone, prasterone, kawain, 5255229, decline, nalbuphine, MK-801, trimethoprim, and GW-8510." (PMID 35799780, 2022).
DiGeorge syndrome (1 paper, 2023). "A 22q11.21 microdeletion encompassing the TBX1, SHANK3, SOX10, AP1B1, FBXO7, MYH9, and SPECC1L genes cause DiGeorge syndrome, which is associated with DD, ID, seizure, and cardiac malformations, with a prevalence of 1 in 4000." (PMID 37189911, 2023).
frontotemporal dementia (1 paper, 2013). Frontotemporal dementia (FTD) comprises a group of neurodegenerative disorders, characterized by progressive changes in behavior, executive dysfunction and language impairment, as a result of degeneration of the medial prefrontal and frontoinsular cortices. "However, changes in several other genes have been suggested as causes for recessive neurological/neurodegenerative disorders that may include PD: hereditary ataxias (ATXN2/3, FMR1), frontotemporal dementia (e.g. MAPT) and others (e.g. ATP13A2, PLA2G6, FBXO7)." (PMID 23976986, 2013).
glioblastoma (1 paper, 2023). The most malignant astrocytic tumor (WHO grade IV). "Targeting the FBXO7‐Rbfox2 axis represents a potential strategy for glioblastoma treatment." (PMID 37822160, 2023). "The authors discover that FBXO7 confers mesenchymal properties and chemoresistance in glioblastoma." (PMID 37822160, 2023).
glioma (1 paper, 2023). A benign or malignant brain and spinal cord tumor that arises from glial cells (astrocytes, oligodendrocytes, ependymal cells). "To gain insight into the functional significance of FBXO7 in GBM, we depleted FBXO7 in a GBM patient‐derived GSC1023 glioma stem cell (GSC) line and then profiled gene expression by transcriptome sequencing." (PMID 37822160, 2023).
Lewy body diseases (1 paper, 2025). "This suggests that the same splicing defects caused by the FBXO7 mutation may also contribute to the pathology seen in Lewy body diseases." (PMID 40950074, 2025).
male infertility (1 paper, 2019). The inability of the male to effect fertilization of an ovum after a specified period of unprotected intercourse. "This proteasomal regulation has also been linked with the male infertility observed in nutcracker deficient flies, with nutcracker suggested to be the Drosophila Fbxo7 orthologue." (PMID 30840666, 2019).
ovarian carcinoma (1 paper, 2022). A malignant neoplasm originating from the surface ovarian epithelium. "In this study, we performed differential expression analysis of circRNAs between ovarian cancerous and normal tissues using rRNA-depleted deep sequencing, and identified a novel circFBXO7 in ovarian cancer, which is produced by back-splicing of exons 2, 3, and 4 of pre-mRNA FBXO7." (PMID 35768865, 2022). "CircFBXO7 was identified as one of the most significantly downregulated circRNAs in ovarian cancer, while its parental gene FBXO7 lacked any significant differential expression between ovarian tumors and normal ovarian tissues." (PMID 35768865, 2022).
Salmonella Infections (1 paper, 2019). Infections with bacteria of the genus SALMONELLA. "Together these data suggest that FBXO7 is required for the normal response to systemic Salmonella infection." (PMID 30840666, 2019). "T cells have been demonstrated to have an important role in mediating the complete clearance of Salmonella infection and given the T cell abnormalities in these mice, we sought to determine the role of FBXO7 within T cells." (PMID 30840666, 2019). "Using T cell-specific Fbxo7 deficient mice (Fbxo7tm1c/tm1c; CD4-Cre+) we repeated the Salmonella infection but observed no weight loss phenotype indicating that there is no role of FBXO7 within mature peripheral T cells for the phenotype observed." (PMID 30840666, 2019).
Sepsis (1 paper, 2024). Sepsis is defined as life-threatening organ dysfunction caused by a dysregulated host response to infection. "Upregulated genes, such as FBXO7, appeared to be the promising peripheral biomarkers of SCM, which are differentially expressed across a series of cell subpopulations (B cell, CD14+ monocyte, and plasma cell) in the peripheral blood of patients with sepsis." (PMID 38291374, 2024).
Stroke (1 paper, 2021). Sudden impairment of blood flow to a part of the brain due to occlusion or rupture of an artery to the brain. "Finally, in the comparison between MCAO-Ngb and MCAO, which demonstrates the effects of the treatment with Ngb-NPs in animals submitted to stroke, the most evident changes involved overexpression of ATXN2l, FBXO7, and NTRK2." (PMID 35008673, 2021). "Of special interest, are proteins such as FBXO7 and NTRK2, which were downexpressed in stroke, but overexpressed after treatment with Ngb-NPs; and ATX2L, which was overexpressed only under the effect of Ngb." (PMID 35008673, 2021). "Specifically, when comparing MCAO vs. sham, proteins FBXO7, WIPI2, NTRK2, A0A0G2JY03, and ITGB8 appeared clearly underexpressed, whereas MAP1a and CPQ were overexpressed, indicating a clear effect of the stroke (MCAO injury) on the individuals." (PMID 35008673, 2021). "Particularly, the ischemic lesion induced the underexpression of FBXO7 and NTRK2, although when stroke animals were treated with Ngb-NPs, both proteins underwent a strong recovery and even overexpression." (PMID 35008673, 2021).
synucleinopathies (1 paper, 2020). "Again, F-box only protein 7 (FBXO7), a substrate recognition component of an E3 ubiquitin-protein ligase complex associated with both UPS and autophagy activity, may be a potential target in synucleinopathies as well." (PMID 32344772, 2020).
T cell lymphoma (1 paper, 2011).
viral infection (1 paper, 2023). "In addition to FBXO7, SIRT7 has also been reported to be polyubiquitinated by HIV-1 Vpr, a multifunctional accessory protein critical for efficient viral infection of target cells." (PMID 36646384, 2023).
cancer (19 papers, 2013 to 2026). A tumor composed of atypical neoplastic, often pleomorphic cells that invade other tissues. "Currently, most studies suggest that FBXO7 primarily functions in cancers by ubiquitinating its substrate proteins and subsequently degrading them through the proteasome pathway." (PMID 41507145, 2026). "FBXO7 exhibits both SCF-dependent and SCF-independent functions, with significant associations to cancer development and progression." (PMID 40896366, 2025). "Building upon our findings, it is important to consider the multifaceted roles of FBXO7 in cellular processes and their implications for cancer biology." (PMID 40896366, 2025). "Compared with its atypical function, the E3 ligase function of FBXO7 is poorly defined, especially in cancer biology." (PMID 38839752, 2024). "We also analyzed the expression of FBXO7 protein via immunohistochemistry (IHC) in our collection of human endometrial normal tissue (25 samples) and cancer tissue samples (117 samples)." (PMID 37344480, 2023). "Though increasing substrates of FBXO7 in cancer and nervous system diseases have been detected, such as Sirtuin 7 (SIRT7), cyclin-dependent kinases (CDK6) and Ubiquitously eXpressed Transcript isoform 2 (UXTV2)." (PMID 37344480, 2023). "FBXO7 is reported to be a tumor suppressor and is involved in cell proliferation and migration in various cancer models." (PMID 37344480, 2023). "And results are consistent with the data from CPTAC that FBXO7 protein is significantly expressed at a lower level in cancer tissues." (PMID 37344480, 2023). "We assessed the requirement for Fbxo7 in over 1,000 cell lines by exploring the Cancer Dependency Map which provides a large-scale analysis of CRISPR-Cas9 screening data, and uses the Chronos algorithm to calculate a measure of gene knockout fitness." (PMID 35670764, 2022). "Cancer cell lines derived from blood and lymphocytic malignancies, which have high expression of Cdk6, show a significant dependency on Fbxo7." (PMID 35670764, 2022). "Previous correlations have reported that FBXO7 is expressed at high levels in cancer and is a potential oncogene." (PMID 35799780, 2022). "Except for USC, MESO, and CHOL, FBXO7 was significantly positively correlated with MKRN1 in the remaining cancers." (PMID 35799780, 2022). "Lastly, we will focus on Fbxo7, an FBP implicated in cancer and neurodegenerative disease, whose atypical functions include regulating cell cycle, differentiation, proteasomal function and mitochondrial quality control." (PMID 24107298, 2013). "Given that dysregulation of the cell cycle is a hallmark of cancer, the pathway involving FBXO7, P27, and CHEK1 may represent an exploitable therapeutic target, particularly for cancers exhibiting FBXO7 copy number losses." (PMID 40896366, 2025). "In summary, our study shows the potential of FBXO7 in future cancer and mitochondrial studies." (PMID 37344480, 2023). "Considering the oncogenic functions of INF2 in cancers, we infer that FBXO7 may inhibit ECa cell proliferation and migration partly in an INF2-dependent manner." (PMID 37344480, 2023). "As our data suggested that Fbxo7 increases PFKP activity, we tested whether Fbxo7 affected glycolysis in cancer cell lines using an Agilent Seahorse to measure the glycolytic rate." (PMID 35670764, 2022). "FBXO7, RAD23A, and MKRN1 are significantly associated with CD8+ T cells in CAD and multiple cancers and may act through immune responses in CAD and cancer." (PMID 35799780, 2022). "As we have demonstrated that hematopoietic and blood cancers are dependent on Fbxo7 expression, future studies on Fbxo7-regulated metabolic pathways in T cell malignancies may reveal actionable vulnerabilities." (PMID 35670764, 2022). "Additionally, as FBXO7 copy number losses occur in multiple cancer types, these findings may have broad-spectrum relevance beyond CRC." (PMID 40896366, 2025). "However, FBXO7 is still poorly studied in cancer biology and even in ubiquitination activity." (PMID 37344480, 2023).
cancer (continued). "Previous genetic studies have shown that heterozygous knockout of SKP1, CUL1, RBX1 and FBXO7 induces CIN, an enabling hallmark of cancer frequently associated with cellular transformation, drug resistance, metastasis and poor patient prognosis in many cancer types." (PMID 35008511, 2021). "Beyond these co-opted E3 ligases, we identified 363 (33.8%) potentially novel E3 ligases highly expressed in over 30 cancer types, such as HUWE1 and FBXO7, indicating the high potential of these E3 ligases for pan-cancer usage." (PMID 37845222, 2023). "It was found that the expression values of FBXO7 were also significantly and positively correlated with the degree of CD8+ T cell infiltration in several cancers, followed by RAD23A and MKRN1." (PMID 35799780, 2022). "This provides a new theory to study the methylation process of FBXO7 and RAD23A and improve potential CAD immune efficacy in cancer patients." (PMID 35799780, 2022). "In addition to LRRK2, several other genes, e.g., α-synuclein, PTEN-induced kinase 1 (PINK1), F-box protein 7 (FBXO7), and ubiquitin C-terminal hydrolase L1 (UCHL1) show altered expression in cancer patients." (PMID 38612708, 2024). "In addition, we found that FBXO7, RAD23A, and MKRN1 were significantly positively correlated in cardiac tissues and most cancers." (PMID 35799780, 2022). "We next analyzed the correlation between FBXO7, RAD23A, and MKRN1 in different cancers." (PMID 35799780, 2022). "In contrast, exploiting defects in a single F-box gene, like FBXO7, may restrict cytotoxicity to cancer cells while sparing normal tissues." (PMID 40896366, 2025). "FBXO7, RAD23A and MKRN1 may act as hub genes linking CAD and cancer in terms of immunity." (PMID 35799780, 2022). "Although the nondegradative effects of Fbxo7-mediated ubiquitination of PFKP in T cells remain to be elucidated, we hypothesize an essential role for Fbxo7 in cancer cell lines in blood lineages is as an activator of Cdk6." (PMID 35670764, 2022).
tumor (10 papers, 2013 to 2026). "Analysis of the clinicopathologic features of tumors in 2 GSE datasets (GSE126964 and GSE73731) revealed that decreased FBXO7 expression was associated with increased tumor stage and grade (T3/T4, G3/G4, and Stage III/IV)." (PMID 41507145, 2026). "Our recent study further implicates FBXO7 deficiency in the disruption of mitotic fidelity and DNA damage response pathways, highlighting its potential importance as a tumor suppressor in colonic epithelial cell contexts." (PMID 40896366, 2025). "It seems that the reported oncogenic role of FBXO7 is related to its E3 ligase-independent function, while both the E3 ligase-dependent and independent functions of FBXO7 are associated with its tumor-suppressive function." (PMID 38839752, 2024). "The effects of FBXO7 in inhibiting midzone division and promoting mitophagy provide evidence that FBXO7 functions as a tumor suppressor and is associated with mitochondrial dynamics." (PMID 37344480, 2023). "This was borne out in experiments showing that over-expression of Fbxo7 in mouse fibroblasts triggered changes associated with cellular transformation, including tumour formation in nude mice." (PMID 24107298, 2013). "In addition, analysis of the clinicopathologic features of the tumors revealed that lower FBXO7 expression was associated with higher tumor stage and grade (T3/T4 and G3/G4) and distant metastasis (M1)." (PMID 41507145, 2026). "Tumor cells with underlying defects in genome maintenance, such as FBXO7 deficiency, are hypothesized to be particularly reliant on CHEK1 function for survival, making CHEK1 inhibition an attractive SL strategy in this context." (PMID 40896366, 2025). "The results confirmed that FBXO7 mRNA expression was significantly lower in tumor tissues than in AN tissues." (PMID 41507145, 2026). "FBXO7 inhibits serine synthesis and tumor growth via ubiquitinating protein arginine N-methyltransferase 1 (PRMT1) in HCC." (PMID 41035649, 2025). "In conclusion, we confirmed FBXO7 as a tumor suppressor in ECa by analyzing its expression data from ECa patients and detecting FBXO7-associated cell models." (PMID 37344480, 2023). "And the receiver operating characteristic curve (ROC) analyses show the area under curve (AUC) value of 0.852 for FBXO7 mRNA and 0.806 for FBXO7 protein to normal and tumor subgroup, respectively, suggesting that FBXO7 is a potential marker for ECa diagnosis." (PMID 37344480, 2023). "Emerging evidence suggests that FBXO7, an F-box protein, plays important regulatory roles in various tumors and could serve as a target for tumor therapy." (PMID 41507145, 2026). "In addition, decreased FBXO7 expression was closely related to distant tumor metastasis, and its expression in metastatic ccRCCs (M1) was significantly lower than that in nonmetastatic tumors (M0) and their AN tissues on the basis of data from GSE105261." (PMID 41507145, 2026). "Similarly, we used a renal orthotopic xenograft tumor growth model to identify the effect of FBXO7 knockdown on ccRCC cell proliferation and metastasis in vivo." (PMID 41507145, 2026). "FBXO7 acts as a tumor suppressor by inhibiting serine synthesis." (PMID 40839607, 2025). "Moreover, immunohistochemical (IHC) staining revealed that tumor tissues with FBXO7 KD exhibited increased levels of PRMT1 protein and PHGDH R236 methylation, which was largely restored by PRMT1 KD." (PMID 38839752, 2024). "In this study, we show a tumor-suppressive role of FBXO7 by inhibiting serine synthesis in HCC." (PMID 38839752, 2024). "Therefore, FBXO7 has a context-dependent dual role in tumor progression, which merits further investigation." (PMID 38839752, 2024). "Moreover, FBXO7 is stabilized by temozolomide, and FBXO7 depletion sensitizes tumor xenografts in mice to chemotherapy." (PMID 37822160, 2023).
tumor (continued). "Therefore, whether FBXO7 regulates the protein stability of certain transcription factors and thereby exerts its tumor-suppressing effect in RCC deserves further research exploration in the near future." (PMID 41507145, 2026). "Thus, our results suggested that HSP90AA1 acts as a tumor suppressor in ccRCC by regulating FBXO7." (PMID 41507145, 2026). "However, recent studies also reveal a tumor-suppressive role of FBXO7." (PMID 38839752, 2024). "Thus, we reason that FBXO7 may play a tumor-suppressive role in ECa by modulating the INF2-DRP1 axis-associated mitochondrial division." (PMID 37344480, 2023). "However, TMZ almost abolished tumor formation of GSCs upon depletion of FBXO7." (PMID 37822160, 2023). "Thus, we investigated whether FBXO7 also acts as a tumor suppressor in ECa." (PMID 37344480, 2023). "Our findings support that FBXO7 negatively regulates INF2-DRP1 axis to inhibit mitochondria division and acts as a tumor suppressor in ECa." (PMID 37344480, 2023). "Because PRMT5‐mediated Rbfox2 methylation is required for Rbfox2 ubiquitination and stabilization by FBXO7, we next explored the potential synergistic effects of FBXO7 silencing plus PRMT5 inhibition on GSC self‐renewal and tumor growth." (PMID 37822160, 2023). "Similar results of FBXO7 protein expression level are found in the ECa database from Clinical Proteomic Tumor Analysis Consortium (CPTAC), suggesting that FBXO7 may act as a tumor suppressor in ECa." (PMID 37344480, 2023). "One hundred and fourteen matched human NSCLC tumor/normal pairs were examined by real-time q-PCR analysis for expression of PARK1/4 (SCNA), PARK2 (Parkin), PARK5 (UCHL1), PARK6 (PINK1), PARK7 (DJ-1), PARK8 (LRRK2), PARK9 (ATP13A2), PARK15 (FBXO7), and GBA mRNA." (PMID 26245297, 2015).